GLO1 (glyoxalase I)
Diseases named in the same sentence as GLO1 in open-access papers (continued):
Sharing a sentence is not in itself a finding about the gene and the disease.
Anxiety (continued). "In the present study we first identified CNVs among inbred mouse strains, and then investigated their relationship to Glo1 expression and anxiety-like behavior." (PMID 19266052, 2009). "However, higher expression of glyoxalase I seems to be correlated with psychiatric problems such as anxiety, something to keep in mind, if such a study should ever be tested as a GNEM treatment." (PMID 36979358, 2023). "Moreover, perinatal administration of methylmercury reduces hippocampal expression of GLO1 and enhances anxiety." (PMID 34953453, 2022). "Additionally, contrary to the findings so far, several reports have shown that Glo1 expression is high in mice with low anxiety." (PMID 34953453, 2022). "In addition, rats that were fed a high-salt diet showed decreased GLO1 expression in the amygdala and hippocampus and enhanced anxiety-like behavior." (PMID 34953453, 2022). "Transgenic mice overexpressing Glo1 displayed an anxiety phenotype." (PMID 34440621, 2021). "Our findings indicate that the effects of hesperidin on ameliorating the depression- and anxiety-like behaviors of diabetic rats, which are mediated by the enhancement of Glo-1, may be due to the activation of the Nrf2/ARE pathway." (PMID 32982741, 2020). "For example, it was hypothesized that Glo1 affects anxiety-related behavior by controlling levels of methylglyoxal." (PMID 26011321, 2015). "Animals with higher copy number of Glo1 exhibited increased anxiety and it is tempting to speculate that this might be behavioral change of adaptive significance in the wild." (PMID 24917877, 2014). "Therefore, this study demonstrated that increased Glo1 copy number increased Glo1 expression and anxiety-like behavior." (PMID 23181072, 2012). "Despite disappointing findings from human genetic studies, there remains a need for large, carefully controlled genetic studies in order to address whether differences in GLO1 affect anxiety among humans." (PMID 23181072, 2012). "BAC transgenic mice overexpressed Glo1 and displayed increased anxiety-like behavior." (PMID 23181072, 2012). "They found a positive correlation between Glo1 expression and anxiety-like behavior." (PMID 23181072, 2012). "As a biomarker of anxiety, altered expression levels of glyoxalase I were reported in mice, compatible with the hypothesis that low MG levels correlate with anxiety, and an anxiolytic effect of MG infusions into brain was demonstrated." (PMID 21248374, 2011). "This contradiction has raised concerns about the role of Glo1 in anxiety-like behavior in mice." (PMID 19266052, 2009). "All data in this paper support a positive relationship between Glo1 and anxiety-like behavior." (PMID 19266052, 2009). "However the observation that over-expression or knockdown of Glo1 altered anxiety-like behavior offers the most compelling evidence that Glo1 is responsible for the observed differences in anxiety-like behavior." (PMID 19266052, 2009). "Thus, the finding is also consistent with those of other studies in that the increase in MG decreases anxiety, although it may contradict them in terms of the amount of Glo1 expression." (PMID 34953453, 2022). "Therefore, to clarify whether Glo1 expression is involved in anxiety in other disease models, rescue experiments by direct manipulation of Glo1 gene expression and MG administration would be necessary." (PMID 34953453, 2022). "However, further investigations are required to shed light on the link between Glo1 and anxiety." (PMID 26011321, 2015). "Thus, previous studies disagree about whether expression of Glo1 increases or decreases anxiety-like behavior." (PMID 19266052, 2009). "While none of these correlations would have been significant if a correction for multiple comparisons (e.g. all CNV identified in this study) had been applied, such corrections were unwarranted because we had a strong prior hypothesis that Glo1 expression affects anxiety-like behavior." (PMID 19266052, 2009).
Anxiety (continued). "There is mounting evidence supporting the role of GLO1 and its substrate (MGO) in the regulation of anxiety-like behaviour." (PMID 36432007, 2022). "It was shown that the difference in Glo1 expression between inbred mouse strains is due to a CNV, the presence of which correlates positively with anxiety-like behavior." (PMID 23659354, 2013). "Significant behavioral impact of Glo-1 was noted only in male GKO mice in the open field and light-dark box tests, which is in agreement with the previous reports claiming correlation between Glo-1/MEG concentration and anxiety-like behavior." (PMID 38187538, 2023). "We cannot rule out the possibility that anxiety in these animal models was triggered by other factors that had a greater impact than decreased Glo1 expression." (PMID 34953453, 2022). "Thus, it is suggested that high GLO1 expression can reduce MG concentration in the brain, thereby decreasing the activity of the GABAA receptor, resulting in enhanced anxiety-like behavior." (PMID 34953453, 2022). "Transgenic mice with 2-fold, 4-fold and 5-fold increased Glo-1 expression had an anxiety phenotype with 4- and 5-fold increased expression but not with 2-fold increased expression." (PMID 27406712, 2016). "It would not be unprecedented if the behavioral effects of Glo1 are sex-specific; sex differences in anxiety have been described in both humans and animal models." (PMID 23181072, 2012). "However, there are no data to show that the decrease in Glo1 expression and subsequent MG accumulation directly affect the enhanced anxiety exhibited in these animal models." (PMID 34953453, 2022). "GLO1′s effects on negative affective changes during protracted abstinence should also be examined, since many of these changes (e.g., increased anxiety- and depression-like behavior) have been seen with genetic and pharmacological manipulation of GLO1 activity in non-dependent mice." (PMID 33478138, 2021). "Although we found the CNV including, amongst others, the Glo1 locus in CD-1 mice and HAB/LAB mice, with more copies and higher expression of Glo1 in LAB mice, our association study in CD-1 mice did not reveal any influence on anxiety-related behavior." (PMID 26011321, 2015). "However, cholecystokinin-tetrapeptide (CCK-4), which is used to induce panic attacks, did not have an effect on GLO1 mRNA levels in peripheral blood cells of 23 healthy volunteers." (PMID 23659354, 2013). "Moreover, selective alteration in the levels of GLO-1, previously reported to be involved in oxidative stress mediated anxiety but not in Cu-Zn SOD and Mn SOD levels is interesting." (PMID 24040270, 2013). "The discovery of the Glo1 CNV also raised the possibility that Glo1 expression could simply be a marker for the presence of the CNV rather than directly regulating anxiety-like behavior." (PMID 23181072, 2012). "Glo1's effect on anxiety-like behavior has not been assessed in females." (PMID 23181072, 2012). "This negative result could reflect inadequate power to detect a difference or could reflect a true lack of effect of a Glo1 duplication on anxiety-like behavior." (PMID 23181072, 2012). "As such, it might not have accurately modeled Glo1's normal physiological role in anxiety-like behavior." (PMID 23181072, 2012). "Moreover, selection for anxiety-like behavior, as measured by the elevated plus maze, produced low-anxiety mice with higher Glo1 expression, suggesting a negative relationship between anxiety-like behavior and Glo1 expression and Glo1 protein levels." (PMID 19266052, 2009). "Finally, naturally occurring copy number variation at the Glo1 locus has been shown to modulate anxiety-like behavior by altering levels of methylglyoxal, a metabolite that acts as a GABAA receptor agonist—thus linking gene dosage and metabolic regulation to neural inhibition and anxiety." (PMID 40689083, 2025). "Thus, no influence of Glo1 expression on anxiety-related behavior could be observed in Fkbp5-/- and Fkbp5+/+ mice." (PMID 26011321, 2015).
Obesity (24 papers, 2013 to 2025). Accumulation of substantial excess body fat. "We not only examined the mechanisms underlying the Glo1 effect on obesity and metabolic dysfunction, but also determined the impact of sex and age over a six-month period." (PMID 39896461, 2025). "Our findings support an important age- and sex-dependent role for Glo1 in mediating obesity and associated comorbidities through alterations of numerous metabolic pathways without major changes in AGEs." (PMID 39896461, 2025). "Conditions associated with metabolic impairment, such as obesity, insulin resistance, and T2D, have been observed to suppress the expression of GLO1, disrupting the MG/GLO1 axis in skeletal muscle metabolism." (PMID 38396716, 2024). "Glyoxalase 1 (Glo1) loss, leading to elevated methylglyoxal (MG) and dicarbonyl stress, has been implicated in various diseases, including obesity-related conditions." (PMID 38668337, 2024). "In leptin-deficient ob/ob mice, a mouse overeating model of obesity, GLO1 protein was decreased in the liver." (PMID 34440621, 2021). "Obesity is a risk factor for chronic diseases during aging and there is increasing evidence supporting a genetic link between Glo1 and obesity." (PMID 34440621, 2021). "GLO1 deficiency is recognized as contributing to the pathogenesis of obesity and diabetic complications." (PMID 29456458, 2018). "We also identified the Glo1 gene because it has been implicated in dietary obesity as a candidate gene and was detected here, too, by differential gene expression analysis." (PMID 23922663, 2013). "These transcriptomic changes in female mice may underlie the obesity, hyperlipidemia, and glucose intolerance phenotypes observed in females Glo1+/− mice." (PMID 39896461, 2025). "Glyoxalase 1 (Glo1) has been linked to obesity, glycemic control, insulin sensitivity, aortic endothelial cell dysfunction, non-alcoholic fatty liver disease (NAFLD), skeletal muscle dysfunction and CVD, suggesting its importance in regulating metabolic health." (PMID 39896461, 2025). "Glo1 has been implicated in various diseases, including obesity-related conditions." (PMID 38668337, 2024). "Altogether, this evidence indicates that the downregulation of GLO1 might lead to cell and tissue dysfunction caused by dicarbonyl stress, which is a potential driver of obesity." (PMID 34440621, 2021). "A meta-analysis of quantitative trait loci in mice linked Glo1 to obesity-related phenotypes." (PMID 34440621, 2021). "If the expression of GLO1/RAGE/DIAPH1 in adipose tissue is altered by increasing degrees of obesity and whether the expression of these genes associates with adipose tissue inflammation and adipocyte metabolism markers was addressed in the present studies." (PMID 34103691, 2021). "Glo-1 has also been implicated in obesity-related conditions." (PMID 31438528, 2019). "Glyoxalase 1 (GLO1) has been implicated in obesity-related conditions." (PMID 29456458, 2018). "Glo1 encodes an enzyme involved in the detoxification of methylglyoxal (a metabolic by-product of glycolysis) and glutathione, and has been linked to dietary obesity in various QTL studies in mice." (PMID 24842286, 2014). "Although Glo1 knockout studies have identified a role for MG-AGE leading to the development of obesity and metabolic dysfunction, the human population rarely exhibits a complete loss of Glo1 activity with an incomplete knowledge of the mechanisms behind Glo1 function." (PMID 39896461, 2025). "To uncover the molecular basis of the obesity and glucose intolerance in female Glo1+/− mice, we profiled the transcriptome of metabolic tissues including gonadal adipose, aorta, and liver in 34-week-old female mice." (PMID 39896461, 2025). "Lastly, along with obesity, the female Glo1+/− mice also demonstrated additional comorbidities such as hyperlipidemia with increased TG and VLDL compared to WT mice." (PMID 39896461, 2025).
Obesity (continued). "Along with the obesity phenotypes, female Glo1+/− mice also demonstrated comorbidities such as glucose intolerance." (PMID 39896461, 2025). "Together, these results suggest that decreased Glo1 expression results in obesity post-developmentally in both female and male in mice." (PMID 39896461, 2025). "The role of dicarbonyl stress in obesity was initially suggested by a genetic linkage analysis in humans where Glo1 was liked to anthropometric measurements of obesity, and later by a meta-analysis of mice strains linking Glo1 to body weight." (PMID 31331077, 2019). "Recent murine data has also provided evidence for reduced GLO1 protein expression with diet induced obesity." (PMID 30250846, 2018). "A consequence of reduced GLO1 protein expression is cellular dicarbonyl stress, which is elevated in obesity, insulin resistance and type 2 diabetes (T2DM)." (PMID 30250846, 2018). "The functional significance of this is indicated by protection from insulin resistance, inflammation and weight gain in Glo-1 transgenic mice in experimental model of over-eating induced obesity." (PMID 27338619, 2016). "Functional genomics studies with Glo-1 in the overfeeding model of HFD-fed mice suggest dicarbonyl stress is a risk factor for health impairment and complications of obesity." (PMID 27338619, 2016). "Increased MG formation from glyceroneogenesis on adipose tissue and liver and decreased Glo-1 activity in obesity likely drives dicarbonyl stress in WAT increasing the dicarbonyl proteome and related dysfunction." (PMID 27338619, 2016). "Increased MG formation by glyceroneogenesis and decreased Glo-1 expression through HIF1α signalling therefore provides the conditions for dicarbonyl stress in obesity." (PMID 27338619, 2016). "In experimental models of obesity there is evidence of decreased Glo-1 activity in visceral adipose tissue." (PMID 27338619, 2016). "Likely drivers of dicarbonyl stress in obesity are: increased formation of MG from increased glycerogenesis in triglyceride synthesis and decreased Glo-1 expression and activity through hypoxia and inflammatory signalling." (PMID 27338619, 2016). "For many years a genetic linkage of Glo-1 to body weight in mice and of GLO-1 to upper-arm circumference and supra-iliac skinfold thickness in human subjects suggested a role for Glo-1 in obesity." (PMID 27406712, 2016). "In the mouse overeating model of obesity, leptin mutant (ob/ob) mice, Glo-1 protein was decreased 80 % in the liver." (PMID 27338619, 2016). "Glo1 has been nominated as a candidate gene for dietary obesity and was differentially expressed in fat and liver tissue in this study." (PMID 23922663, 2013). "Importantly, the concurrent upregulation of Fasn and Dgat2 in gonadal adipose is consistent with the obesity phenotype observed in Glo1+/− mice." (PMID 39896461, 2025). "Therefore, together with the increased MGO formation from glyceroneogenesis, Glo1 downregulation by hypoxia and inflammation provide the conditions for dicarbonyl stress in obesity." (PMID 31331077, 2019). "Skeletal muscle GLO1 is reduced in mice fed a high-fat diet, but whether diet or obesity has independent effects on skeletal muscle GLO1 in humans has yet to be determined." (PMID 30250846, 2018). "Glo-1 down regulation in obesity may be driven through hypoxia signalling by hypoxia-inducible factor-1α (HIF1α), which down-regulates Glo-1 expression." (PMID 27338619, 2016). "Additionally, increased weight gain in mice lacking Glo1 fed with high fat diets and decreased weight gain and adiposity in Glo1 overexpressing transgenic mice with high fat diet have been observed, supporting a functional role of GLO1 and dicarbonyl stress in obesity." (PMID 34440621, 2021).
Obesity (continued). "Notably, recent observations suggest that excess MG due to inhibition or genetic deletion of glyoxalase 1 (Glo1) promotes obesity and impairs glucose metabolism and insulin resistance (IR); likely by altering adipose tissue vascularization and promoting its expansion." (PMID 34103691, 2021). "In our previous clinical study of treatment of subjects with overweight and obesity with tRES + HESP, the pharmacological target validation of the Nrf2-dependent induction of increased Glo1 expression and activity was achieved." (PMID 40867918, 2025). "Overexpression of Glo-1 prevented insulin resistance and inflammation in HFD-fed mice, suggesting a functional role of dicarbonyl stress in obesity." (PMID 27338619, 2016). "These enzymes were glucose 6-phosphate isomerase (GPI), triosephosphate isomerase (TPI), enolase (Eno3), lactate dehydrogenase (LDHa), glyoxalase-1 (Glo1) and the mitochondrial DLD, whose expressions were modified by AM251 in hypercaloric diet-induced obesity." (PMID 26671069, 2015). "In summary, our findings support the role of Glo1 reduction in modulating obesity and metabolic dysfunction in a sex specific manner without strong evidence for the involvement of AGEs." (PMID 39896461, 2025). "Despite the known role of the MG-AGE pathway in obesity and metabolic dysfunction, previous studies in fish and mice have revealed that full Glo1 knockouts, does not always result in elevated MG, AGEs or even an observable phenotype, likely through compensation of ALDH and AKR." (PMID 39896461, 2025). "Despite the current state of the literature, we cannot differentiate independent effects of obesity, insulin resistance or clinical T2DM on GLO1 protein expression or enzymatic activity; nor can it be determined if reductions in GLO1 are causative or a consequence of metabolic pathologies." (PMID 30250846, 2018).